ALB (albumin)
Diseases named in the same sentence as ALB in open-access papers (continued):
Sharing a sentence is not in itself a finding about the gene and the disease.
Cirrhosis (continued). "Several studies have highlighted the impact of cirrhosis, the Child–Pugh class, albumin levels, and prolonged prothrombin time on recurrence rates." (PMID 39766066, 2024). "A decrease in serum albumin possibly suggests inflammation, chronic infections, kidney problems, and cirrhosis, among others." (PMID 38741871, 2024). "Improving patient conditions with individuals suffering from decompensated cirrhosis was also made possible by administering chronic, high-albumin dose (HAlbD) treatments." (PMID 39099956, 2024). "A study investigated on the prevalence of cirrhosis-induced post-transcriptional changes to albumin and how this affected cirrhotic patient outcomes." (PMID 38551716, 2024). "Supplementation with functional albumin molecules has been shown to be beneficial for infection control in patients with cirrhosis." (PMID 39039452, 2024). "Skeletal muscle mass is a more accurate representation of nutritional status than solely relying on serum albumin levels in patients with cirrhosis and HCC." (PMID 38254808, 2024). "The structural integrity of albumin plays a very important role in cirrhosis patients because of albumin's anti-inflammatory and antioxidant functions." (PMID 38551716, 2024). "The Child-Pugh-Turcotte score, commonly used to predict outcomes for cirrhosis, includes albumin as one of its components." (PMID 38561807, 2024). "Older age, male gender, low serum albumin levels, and high LSM were risk factors for HCC after SVR in hepatitis C patients with advanced fibrosis and cirrhosis." (PMID 38664813, 2024). "Based on these findings, the use of albumin in critically ill patients with cirrhosis and AKI should be approached with greater consideration of its risks and benefits, exercising more caution in clinical practice." (PMID 39434907, 2024). "Long-term albumin (LTA) is currently standard of care for patients with decompensated cirrhosis in many Italian hepatology centres." (PMID 39640220, 2024). "The ALBI score is a predictor of cirrhosis mortality, including two parameters of albumin and bilirubin." (PMID 38191888, 2024). "In the cirrhosis cohort, PC 32:0 was negatively correlated (r = −0.552, p = 0.005) and PC 38:4 was positively (r = 0.509, p = 0.018) correlated with albumin." (PMID 39125730, 2024). "In hepatic conditions, albumin serves as an excellent marker for liver function in patients with chronic liver disease and cirrhosis." (PMID 39199720, 2024). "Bortulozzi and coworkers used carbon tetrachloride (CCl4) to induce cirrhosis and ascites in rats, subsequently infusing intravenous albumin to determine its effects on the cirrhotic heart." (PMID 38892040, 2024). "OxPTMs play an important role in several diseases, e.g., ox‐induced dimerization of albumin was identified in patients diagnosed with chronic liver disease. and cirrhosis." (PMID 38958560, 2024). "Determination of these cirrhosis-induced structural alterations in albumin has shown prognostic value." (PMID 38551716, 2024). "Albumin levels are a strong predictor of mortality in numerous studies of individuals with cirrhosis, making it an essential prognostic factor." (PMID 38561807, 2024). "The impact of albumin administration timing on hospital resource utilization and its optimal timing is unclear, despite its efficacy in improving survival for cirrhosis patients with spontaneous bacterial peritonitis." (PMID 38899040, 2024). "A prospective study found that high-dose albumin infusion reduced plasma cytokine levels and significantly reduced systemic inflammatory responses in patients with cirrhosis." (PMID 39039452, 2024). "Even in patients with cirrhosis or cardiac failure, we measured both very low calciuria and low serum calcium levels, which was due to the low albumin concentration in these patients." (PMID 36675652, 2023). "Albumin infusions have long been used for the management of complications of cirrhosis to improve plasma oncotic pressure and alleviate ascites and peripheral edema." (PMID 37019645, 2023).
Cirrhosis (continued). "Regarding minerals, the median values of potassium, albumin-corrected total serum calcium and magnesium were significantly lower in the cirrhosis cases (p < 0.05)." (PMID 37371636, 2023). "In line with previous studies, COVID-19 patients with cirrhosis had higher levels of liver transaminases and liver function parameters and lower albumin levels on admission." (PMID 37371636, 2023). "Our study aimed to investigate the prognostic value of neutrophil count to albumin ratio (NAR) in predicting short-term mortality of patients with decompensated cirrhosis (DC)." (PMID 38007536, 2023). "More than half of the patients who consulted emergency services for acute decompensation of cirrhosis required the use of antibiotics, approximately one in three received blood products, and one in four required vasopressor support and human albumin infusion." (PMID 38207155, 2023). "Comparative studies of long-term albumin use in decompensated cirrhosis, as observed in the ANSWER and MACHT trials, offer insights." (PMID 38139434, 2023). "ANSWER trial reported the beneficial effects in terms of survival of long-term albumin infusions in patients with decompensated cirrhosis." (PMID 37396918, 2023). "Among patients with liver involvement those with cirrhosis had significantly lower fetuin-A and albumin level, white blood cell and platelet count." (PMID 36881584, 2023). "Reasons include the progression of hepatic cirrhosis, IPI and FLIPI risk factors, low albumin, and the maintenance of a certain level of HCV-RNA." (PMID 37345190, 2023). "Albumin in cirrhosis effectively addresses fluid imbalance, circulatory dysfunction, and inflammation, particularly in the management of post-paracentesis circulatory dysfunction, HRS-AKI, and SBP." (PMID 38139434, 2023). "Such adverse effects were documented in a recent trial aimed at increasing albumin levels above 30 g/L in patients with decompensated cirrhosis." (PMID 36908849, 2023). "One study pointed out that the albumin function of patients with advanced cirrhosis significantly decreased." (PMID 37715140, 2023). "The ATTIRE trial was a randomized, multicenter evaluation involving hospitalized patients with decompensated cirrhosis who had a serum albumin level of less than 30 g per liter at the time of enrollment." (PMID 37218881, 2023). "Albumin administration is potentially effective in managing cirrhosis-related complications, including immune and circulatory dysfunctions." (PMID 38139434, 2023). "This is reflected by the consequent positive correlation between fetuin-A and serum albumin in alcoholic cirrhosis, primary biliary cholangitis (cirrhosis) and in Wilson’s disease, in the current study." (PMID 36881584, 2023). "Albumin appears to be a promising immunomodulating strategy in cirrhosis, though more clinical evidence is required." (PMID 37822786, 2023). "In cirrhosis SM 36:2;O2 (r = 0.815, p < 0.01) and 38:2;O2 (r = 0.768, p < 0.05) positively correlated with albumin levels." (PMID 37176109, 2023). "It is well known that albumin is produced by the liver, so when patients suffer from severe liver disease or cirrhosis, it can affect albumin levels." (PMID 38114922, 2023). "Further subgroup analyses in the context of cirrhosis should be conducted to clarify the use of albumin in various segments of patients with cirrhosis." (PMID 39132612, 2023). "In severe liver fibrosis and cirrhosis, albumin synthesis is hindered, lowering albumin concentration." (PMID 38137829, 2023). "The INFECIR-2 study investigated the impact of short-term antibiotics alone versus a combination of albumin and antibiotics on cytokine levels in 78 patients with decompensated cirrhosis and bacterial infections." (PMID 38139434, 2023). "In a multivariate logistic regression assessing mortality based on gender and cirrhosis severity, Na, albumin, INR, direct bilirubin, WBC and CTP remained significant risk factors for mortality in COVID-19 patients with cirrhosis." (PMID 37371636, 2023).
Cirrhosis (continued). "This review examines the various applications of albumin in cirrhosis, highlighting its roles beyond volume expansion, such as antioxidant effects and inflammation modulation." (PMID 38139434, 2023). "There is, however, a need to rationalize the use of albumin therapy in different types of liver disease and stages of cirrhosis and to determine the optimum dose, duration, and frequency of albumin in each situation." (PMID 37432160, 2023). "Albumin and rifaximin are drugs that already have a formal indication to treat several complications of cirrhosis and portal hypertension." (PMID 36769582, 2023). "In this study, we aimed to assess the value of network mapping in predicting response to targeted albumin therapy in patients with cirrhosis." (PMID 37019645, 2023). "In the future, more relevant clinical trials are needed to validate the efficacy of albumin infusion therapy and the doses used for cirrhosis combined with HE." (PMID 37770848, 2023). "Recently, the BE3A score, which consists of body mass index (BMI), HE, ascites, ALT levels and albumin levels, was reported to be useful for predicting patients whose CP class improved to CP-A among patients with decompensated cirrhosis treated with DAA." (PMID 37831182, 2023). "The number of randomized controlled trials and observational studies published on albumin in the setting of cirrhosis reveals the great interest of hepatologists in this molecule." (PMID 36769582, 2023). "Albumin plays a critical role in the management of cirrhosis-related complications, including ascites, HRS, AKI, and SBP." (PMID 38139434, 2023). "The four groups were statistically different in gender, age, tumor size, MVI, BCLC stage, cirrhosis, albumin, ALT, AFP, NEUT, EO, and LYMPH (P<0.05)." (PMID 36638133, 2023). "This is a substudy of the ATTIRE trial, a multicenter randomized trial conducted to assess the effect of targeted albumin therapy in cirrhosis." (PMID 37019645, 2023). "Nearly one third of patients with cirrhosis receiving standardized albumin infusions develop volume overload." (PMID 36866858, 2023). "The HCC group had significantly higher levels of total bilirubin, aspartate aminotransferase, alanine aminotransferase, alkaline phosphatase, and AFP but a lower level of albumin than the cirrhosis and healthy groups." (PMID 36673067, 2023). "In the univariate analysis, CP score, total bilirubin, albumin, PT, IGF-1, and M2BPGi were significantly associated with decompensation development in patients with compensated cirrhosis." (PMID 37554499, 2023). "In this regard, among humans, there is evidence of elevated levels of serum enzymes alkaline phosphatase and transaminase and low plasma levels of albumin, which are attributed to hepatic cirrhosis and cholestasis." (PMID 37375509, 2023). "The study concluded that L-FABP, along with three other biomarkers (NGAL/Neutrophil gelatinase-associated lipocalin, IL-18/Interleukin-18, and albumin), has a good and efficient ability to differentiate patients with progressive AKI and cirrhosis." (PMID 38136624, 2023). "A recent umbrella review of meta-analyses indicated that high-dose, short-, and long-term albumin infusion significantly reduced mortality in patients with cirrhosis." (PMID 38139434, 2023). "GA levels are related to the total albumin levels, which affect patients with protein-losing states such as hepatic cirrhosis, nephrotic syndrome, and thyroid disease." (PMID 37818560, 2023). "Our data suggest that total serum calcium corrected for albumin is an accurate and highly sensitive prognostic factor that can be used to predict mortality in COVID-19 patients with cirrhosis." (PMID 37371636, 2023). "In conclusion, our study highlights the potential benefits of prompt albumin use in patients with decompensated cirrhosis and acute renal dysfunction." (PMID 39132612, 2023). "In summary, the effectiveness of albumin in decompensated cirrhosis is heavily influenced by the dose and duration of administration." (PMID 38139434, 2023).
Cirrhosis (continued). "Albumin is one of the mainstays of treatment in some significant cirrhosis-related complications: paracentesis induced circulatory dysfunction (PICD), acute kidney injury-hepatorenal syndrome (AKI-HRS), and spontaneous bacterial peritonitis (SBP)." (PMID 36769582, 2023). "Future studies should further investigate the value of WCC-CRP and network mapping to predict outcome in decompensated cirrhosis and improving selection of patients for further trials of albumin or other immune-/inflammation-modulating therapies." (PMID 37019645, 2023). "As expected, patients with cirrhosis had significantly lower serum concentrations of albumin, transferrin, transthyretin, pseudocholinesterase, and apolipoprotein AI compared to healthy individuals." (PMID 36652164, 2023). "CART is safe and effective as a treatment option for large‐volume paracentesis with the infusion of albumin for cancer or cirrhosis." (PMID 37180320, 2023). "A Meta-analysis of human albumin infusion for cirrhosis and its complications found that in cirrhosis patients with overt HE, albumin infusion improved the severity of overt HE but not overall mortality." (PMID 37770848, 2023). "Long-term administration of albumin can modify the course of decompensated cirrhosis by reducing the onset of new complications, improving the quality of life, and probably providing survival benefits." (PMID 37432160, 2023). "The highest-quality evidence exists for the use of albumin in patients with cirrhosis, particularly for the treatment of SBP, HRS, and large-volume paracentesis (>5 L)." (PMID 37218881, 2023). "On univariate analyses for factors contributing to grade ≥ 2 GP-induced liver injury, the significant factors were age, weight, BMI, cirrhosis, platelet count, PT, albumin, TB, and ALBI grade." (PMID 36851703, 2023). "Among patients with cirrhosis and AKI, treatment with albumin ≤24 hours after admission was associated with a shorter LOS and lower risk of death in patients with stage 3 AKI." (PMID 39132612, 2023). "Albumin, the most abundant and arguably most important protein in the human body, plays a unique role in decompensated cirrhosis because its structure and function are quantitatively and qualitatively affected." (PMID 37013893, 2023). "A pilot study of patients with cirrhosis revealed that IGF-1 administration for 4 months increased serum albumin levels and improved energy metabolism, as assessed by resting energy expenditure." (PMID 37554499, 2023). "Compared to the cirrhosis group, the albumin level was significantly lower in the HCC group, while the remaining serum parameters were not significantly different." (PMID 36793057, 2023). "For example, as an emergency therapy, albumin has been used in patients with cirrhosis and ascites and in patients with acute ischemic stroke for many years." (PMID 35741308, 2022). "The administration of intravenous human albumin has been utilized in cirrhosis patients in various settings, such as after large-volume paracentesis, in the long-term management of decompensation and in spontaneous bacterial peritonitis." (PMID 36721617, 2022). "The search terms used were “albumin”, “cirrhosis”, “spontaneous bacterial peritonitis” and “efficacy”." (PMID 36721617, 2022). "Previous report demonstrated that the structure of circulating albumin, assessed by HNA, more accurately predicted the outcomes of patients with cirrhosis than serum albumin concentration did." (PMID 36555935, 2022). "Human albumin has many other characteristics, some of which are particularly significant in relation to the chronic inflammatory condition of decompensated cirrhosis." (PMID 36721617, 2022). "There is now general agreement on the impact of the MELD score, hepatic encephalopathy, hyponatremia, and indicators such as ALB, bilirubin, and renal function on the overall poor prognosis of patients with decompensated cirrhosis." (PMID 36148461, 2022).
Cirrhosis (continued). "This meta-analysis aimed to determine the impact of intravenous human albumin in patients with cirrhosis and SBP." (PMID 36721617, 2022). "Patients with MVI and patients without were similar in their distribution of sex, hepatic virus infection, cirrhosis, Child-Pugh stage, TB, CB, ALB, and PT." (PMID 35676669, 2022). "On the other hand, albumin levels can decline rapidly particularly in patients with advanced fibrosis and cirrhosis because of reduced synthesis by hepatocytes." (PMID 34983435, 2022). "The mechanism through which albumin infusion enhances circulatory functions in patients with cirrhosis and SBP is by enhancing the cardiac overload and venous return." (PMID 36721617, 2022). "In the present study, age, platelet count, serum albumin level, HBeAg positivity, and LS value remained independent or tended to be associated with HCC development in patients with HBV-related cirrhosis." (PMID 36611295, 2022). "Certain randomized control trials (RCTs) have been conducted that investigated the effect of albumin on cirrhosis and bacterial infections, but the existing studies were underpowered for detecting the possible benefits of intravenous human albumin." (PMID 36721617, 2022). "Although the percentage of patients with HCV-cirrhosis was similar among albumin levels, a recent study showed lower albumin levels in patients with HCV viremia at HCC diagnosis compared to aviremic patients treated with direct-acting antivirals (DAA)." (PMID 35406456, 2022). "When liver failure or cirrhosis occurs, the production of albumin as a molecule in the albumin to globulin ratio decreases, resulting in a low ALB:GLO value." (PMID 35514333, 2022). "Taking patients stratified according to the cirrhosis score, health status (albumin, height, weight, and BMI), and race, we analyzed those patients in different subgroups using the KM curve." (PMID 36246406, 2022). "There were five variables related to the severity of cirrhosis (CTP score, PT, bilirubin, albumin, and MELD score) and three related to cirrhosis-associated complications (encephalopathy, GI hemorrhage, and HCC)." (PMID 35139804, 2022). "Impaired synthetic functions of proteins resulting from hepatic cirrhosis need to be considered as an additional determinant for the decrease in serum albumin." (PMID 35846958, 2022). "Several studies have shown that serum albumin is an important prognostic factor and a significant predictor of death in patients with cirrhosis and also a predictor of serious non-AIDS events in PWH." (PMID 36303554, 2022). "The variables screened by Lasso regression including age, gender, cirrhosis, tumor number, tumor size, platelet-albumin-bilirubin index (PALBI), and viral load were incorporated in the Cox model and random survival forest model (P<0.05)." (PMID 36505501, 2022). "The Child-Turcott-Pugh classification considers five variables (serum bilirubin, albumin, prothrombin time, ascites, and hepatic encephalopathy), with higher classifications indicating worse prognosis in patients with cirrhosis." (PMID 36404314, 2022). "Nevertheless, although there are no studies in patients with proteinuria, many studies demonstrate that CAR is a good predictor of mortality in patients with decompensated cirrhosis, a condition that involves low albumin values." (PMID 36006278, 2022). "We and others have also previously demonstrated potential immunomodulatory or anti-inflammatory effects of albumin infusions in hospitalized patients with complications of cirrhosis." (PMID 35333783, 2022). "At sacrifice, the CCl4 treatment group displayed an altered pattern of the biochemical indexes of cirrhosis, namely high cholestasis and low ammonia values, altered liver function and low levels of serum albumin." (PMID 35160088, 2022). "When liver function is damaged in cirrhosis, albumin and coagulation factor synthesis are decreased." (PMID 36241992, 2022).